VN1R1 (vomeronasal 1 receptor 1)
Description:
Putative pheromone receptor.
Synonyms: V1RL1; VNR19I1; ZVNR1; ZVNH1
Tractability: Small molecule: it belongs to a druggable protein family. Antibody: UniProt places it where antibodies can reach, with medium confidence; UniProt predicts a signal peptide or a membrane-spanning region; its Gene Ontology location is reachable by antibodies, with medium confidence.
Gene: Protein-coding gene on chromosome 19 (57,454,790 to 57,457,140, reverse strand). Ensembl gene ENSG00000178201.
Subcellular location: Cell membrane
Subcellular location (Human Protein Atlas): Vesicles; Nucleoplasm
Gene Ontology:
Molecular function: pheromone binding; pheromone receptor activity
Biological process: G protein-coupled receptor signaling pathway; sensory perception of chemical stimulus
Cellular component: plasma membrane; membrane
Genetic constraint (gnomAD): Missense variants: 391 observed, 431.1 expected, observed/expected ratio (o/e) 0.91, 90% interval 0.83 to 0.99. Synonymous variants: 168 observed, 157.44 expected, observed/expected ratio (o/e) 1.07, 90% interval 0.94 to 1.21.
Homologues: Orthologues: chimpanzee VN1R1 (95% identical), rabbit VN1R1 (58% identical). Paralogues in human: VN1R4 (37% identical), VN1R2 (36% identical), VN1R5 (22% identical).
Diseases named in the same sentence as VN1R1 in open-access papers:
VN1R1 is named in the same sentence as 4 diseases in open-access papers, as found by Europe PMC text mining. Sharing a sentence is not in itself a finding about the gene and the disease. The quoted sentences say what the papers report.
prostate adenocarcinoma (1 paper, 2019). "Among them, VN1R1 has been shown to be overexpressed in prostate adenocarcinomas and glioblastoma cancer cells and POTED in prostate cancer patients, making it a potential molecule for targeted therapy." (PMID 31242667, 2019).
VN1R1 also shares sentences with these, for which no sentence is quoted: Anxiety (1 paper); cancer (1); prostate carcinoma (1).